CXCR2 (C-X-C motif chemokine receptor 2)
Diseases named in the same sentence as CXCR2 in open-access papers (continued):
Sharing a sentence is not in itself a finding about the gene and the disease.
cancer (continued). "Several studies have explored CXCR2 antagonists in therapeutic strategies for cancer." (PMID 40124384, 2025). "This supports the possibility that cancers can develop resistance to CXCR2 inhibition via the upregulation of HIF1A or MYC expression and suggest that combining drugs targeting CXCR2 and HIF1A or MYC may increase their therapeutic efficacy." (PMID 40050422, 2025). "The therapeutic effect of CXCL5 neutralization on cancer cachexia may depend on whether CXCR2 signaling contributes to these differences in cachexia progression observed in males and females." (PMID 41392310, 2025). "Furthermore, cancer-associated fibroblasts are shown to enhance TAM recruitment via the CXCL12/CXCR4 axis in breast cancer and the IL-8/CXCR2 axis in CRC." (PMID 40380196, 2025). "However, as a selective CXCR2 antagonist, SB-225002 has demonstrated promising therapeutic activity across multiple other cancer types through diverse mechanisms." (PMID 41585903, 2025). "Similarly, CXCR1/CXCR2 inhibition with the small molecule inhibitor ladarixin diminished the presence G-MDSCs near EY epithelia basement membranes and decreased carcinoma incidence and burden in EY mice." (PMID 39779672, 2025). "However, studies using double-knockout mice for CCR1 and CXCR2 remain unexplored in cancer research." (PMID 38750114, 2024). "More precisely, MIF downregulated the interaction between cancer-associated fibroblasts and immune cells including B cells, DCs, myeloid derived suppressor cells, monocytes, NK cells, and T cells via the CD74/CD44 and CXCR2/CXCR4 signaling pathways." (PMID 38638429, 2024). "The ITGB2, CSF1, and CXCR2 genes are closely related to cancer." (PMID 39771147, 2024). "The binding of chemokines to this receptor may inhibit the activity of CXCR2 if both receptors are located on the same cancer cell." (PMID 37686093, 2023). "CXCR2 expression was significantly associated with cancer nest MMP9 expression (p = 0.010) whereas CXCR1 was not (p = 0.591)." (PMID 37296952, 2023). "For this reason, several reports suggest that inhibition of CXCR-2 or IDO-1 may be therapeutically helpful in many human cancers." (PMID 37626777, 2023). "CXCR2 inhibitors are now available in clinical trials as adjunctive cancer therapies." (PMID 37210553, 2023). "IDO-1 or CXCR-2 have previously been reported to inhibit cancer cell apoptosis." (PMID 37626777, 2023). "Several in vitro and in vivo studies revealed that CXCR2 antagonize resulted in a great cancer progression as well as metastasis inhibition; thus, it could be a promising strategy for cancer therapy." (PMID 38067251, 2023). "Indeed, the activation of CXCR2 signaling promotes angiogenesis in cancer, as well as in chronic ischemic and inflammatory diseases." (PMID 36511116, 2023). "The past decade has witnessed the generation and development of antagonists to CXCR1 and CXCR2, and multiple clinical trials are underway investigating the therapeutic potential of targeting this signaling axis in inflammatory disorders and cancers (NCT03161431, NCT04245397, NCT03400332)." (PMID 37270599, 2023). "Increased CXCR2 expression on cancer cells transforms these cells into neuroendocrine cancer cells." (PMID 37108425, 2023). "The expression of ligands for CXCR2 by bone marrow adipocytes may support the formation of cancer bone metastasis in elderly or obese people." (PMID 35457023, 2022). "Indeed, we found that CXCR2 inhibition blocked the macrophage-induced cancer cell invasion for both cell lines." (PMID 35998057, 2022). "CXCR2 is involved in therapy resistance by maintaining and promoting the migration of cancer stem cells (CSCs), and it is not only suggested as a novel cancer stem-like cell marker for TNBC but also known to regulate TGF-β signaling, which is known to promote chemotherapy resistance." (PMID 35517812, 2022). "Besides, CXCR2 was up-regulated in cancer stem cells (CSCs) and promotes the growth and migration of CSCs." (PMID 35963638, 2022).
cancer (continued). "In human cancers, the function of CXCR2 has been scarcely investigated so far." (PMID 34066060, 2021). "For example, although anti-PD1 therapy is an effective cancer treatment, the overexpression or mutations of LAMA3, CXCR2, and JAK1/2 could prevent the immune system from boosting effective antitumor immunity." (PMID 34660300, 2021). "In the context of cancer, CXCR2 plays a major role in the recruitment of MDSCs to the TME." (PMID 34944914, 2021). "As immunotherapies gain approval for a wider variety of cancer types and stages, it will become more important to better understand the particular indications for which CXCR2 inhibition may provide synergistic benefit when paired with immunotherapy." (PMID 34944914, 2021). "The results revealed that CXCR2 is a potential anti‐angiogenic target in malignant tumors." (PMID 34497764, 2021). "However, as immunotherapy moves toward approval for earlier-stage cancers, the potential benefit of adding a CXCR2 antagonist to improve responses warrants investigation." (PMID 34944914, 2021). "However, due to oncogenic role of CXCR2 in a lot of cancers, we infer that CXCLs/CXCR2 signal is essential for normal/preneoplastic cells to maintain response to oncogenic senescence signal." (PMID 33814009, 2021). "We found that cancer stem-like cell cluster LuE2 highly expressed Cxcl1, while the immune cells from cluster 8 defined as macrophages specifically highly expressed the corresponding receptor, Cxcr2." (PMID 34675206, 2021). "Survival analysis uncovered the prominent prognostic significance of CXCR2 in diverse cancer types." (PMID 34840630, 2021). "Due to the associations between high MDSC infiltrates and therapy resistance across cancer types, tumors with high levels of MDSCs or patients who have developed resistance to prior lines of therapy may benefit from treatment with a CXCR2 antagonist." (PMID 34944914, 2021). "Furthermore, CXCR2 arises as an unprecedented target to fight cancer in the adjuvant setting by overcoming chemotherapy resistance." (PMID 34038868, 2021). "Correlation between CXCR2 expression and neoantigens was assessed in diverse cancer types." (PMID 34840630, 2021). "In a study, knockdown of CXCR-2 expression in cancer cells could improve the efficiency of paclitaxel, reducing metastases in the lungs." (PMID 34336101, 2021). "CXCR1 and CXCR2 are reported to promote proliferation and invasion in many cancer cells." (PMID 34277625, 2021). "The relationship of CXCR2 with macrophage has been reported in several cancer types." (PMID 34840630, 2021). "Our findings confirm the anti-cancer effects and safety of CXCR2 targeted therapy." (PMID 33814009, 2021). "Notably, it has been reported that the axis connecting CXCL1 and its receptor, CXCR2, a G protein-coupled receptor, plays significant roles in mediating the communication between cancer cells and the microenvironment of gastric and bladder tumors." (PMID 33941851, 2021). "Staining of cancer cells would definitely alter the value of CXCR2 for outcome." (PMID 32727083, 2020). "Moreover, CXCR1 and CXCR2 expressed on immune cells can promote the recruitment of cancer microenvironment, thus affecting cancer invasion and metastasis." (PMID 33324682, 2020). "CXCL3 could bind to the chemokine receptor CXCR2 and regulates the progression and metastasis of malignant tumor." (PMID 32430842, 2020). "Also, CXCR2 and 4 receptors found on both stem/progenitor and cancer cells can influence both stem/progenitor cells' homing and cancer cells' invasion/metastases." (PMID 33953753, 2020). "Inhibition of CXCR2 suppressed cancer cell migratory and invasive behavior enhanced by necroptosis." (PMID 31999765, 2020). "Additionally, some investigations showed that mast cells also expressed chemokine receptors such as CXCR1 and CXCR2 in different cancers." (PMID 30808413, 2019).
cancer (continued). "Of these genes, CXCL12, a chemokine and its cell surface receptor, CXCR4, and CXCR2 which are known to be involved in cancer cell proliferation and metastasis were verified by qRT-PCR to be significantly increased by ~3-fold in the HCC97L cells transfected with the CPE-ΔN expression plasmids." (PMID 31798768, 2019). "Future research will be required to determine whether complete removal of CXCR2 is sufficient to overcome CXCL5-induced cancer cell proliferation or whether other CXCL5-bound receptors contribute." (PMID 31562303, 2019). "Since emerging evidence suggests that CXCR2 could be a druggable target in cancer therapy, the development of CXCR2 inhibitors has received much attention in recent years." (PMID 31390756, 2019). "We added antCXCR2 to the culture media of IC-primed bone cultures, which support cancer cell proliferation, to determine whether CXCR2 inhibition was sufficient to inhibit cancer cell proliferation." (PMID 31562303, 2019). "In another recent example using the 4T1 TNBC mouse model, it was shown that CXCR2+ MDSCs induces cancer cell EMT by IL-6 and these CXCR2+ MDSCs promotes T cell exhaustion, suggesting that CXCR2+ MDSCs may be a potential therapeutic target of TNBC." (PMID 31075939, 2019). "In addition, growing evidence has demonstrated that CXCR2 plays pivotal roles in the progression of various cancers." (PMID 30984000, 2019). "More importantly, inhibition of MDSC recruitment by blocking the CXCR2 signaling enhances the entry of NK cells into tumors and lymph nodes, which may restore anti-cancer immunity in vivo." (PMID 31390756, 2019). "Inhibition of CXCR2 by SB225002 attenuated the upregulation of SAA1 by LECs co-cultured with LC cells, suggesting that LEC-derived chemokines may reciprocally activate SAA1 expression in cancer cells via CXCR2." (PMID 31390756, 2019). "Importantly, CRC association was found for two genes in the previously reported 2q25 locus, CXCR1 and CXCR2, which are potential cancer therapeutic targets." (PMID 30820706, 2019). "Besides, the highlighted role of CXCR2 in several cancers was first explored synthetically in this meta-analysis." (PMID 29599927, 2018). "Compound 1e was further studied for its high anti-metastatic potency in the NCI-H1299 cell line, suggesting that it could be used as a good hit compound for CXCR2 antagonism and as an anti-cancer metastatic agent." (PMID 30109074, 2018). "In addition to clear evidence of a role for CXCR2 in cancer progression, CXCR2 is known to influence oncogene-induced and replicative senescence through a DNA-damage." (PMID 29515768, 2018). "The molecular mechanism of CXCR2 in cancer progression may include various signaling pathways such as mitogen-activated protein kinase (MAPK), phosphoinositide 3-kinase (PI3K), signal transducer and activator of transcription 3 (STAT3) and NF-κB pathways." (PMID 29515768, 2018). "Clinical trials evaluating reparixin, a CXCR1 and CXCR2 inhibitor, are ongoing in cancer patients." (PMID 30304046, 2018). "Therefore, this study, aimed to summarize prominent studies and determine the clinical efficacy of CXCR2 in predicting the prognosis of cancer patients, was carried out." (PMID 29599927, 2018). "The expression of CXCR2 in stromal cells was correlated with macroscopic type-4 cancers, histological type, T invasion (T2–T4), lymph node metastasis, lymphatic invasion, infiltration, peritoneal cytology, peritoneal metastasis and CD271 expression in stromal cells." (PMID 28575019, 2017). "In addition, recent experimental evidence has highlighted an important role for CXCR2 in cancer formation and maintenance." (PMID 28205614, 2017). "CXCR2 expression in stromal cells was significantly correlated with macroscopic type-4 cancers, histological type, T invasion (T2–T4), lymph node metastasis, lymphatic invasion, infiltration, peritoneal cytology, peritoneal metastasis and CD271 expression in stromal cells." (PMID 28575019, 2017).
cancer (continued). "In this sense, disrupting the GRO-α-CXCR2 axis in NMIBC may represent a promising alternative to prevent post-chemotherapy cancer progression and recurrence." (PMID 28423359, 2017). "Further studies will be required to determine whether CXCR2 blockade has a favorable effect on the prognosis of patients with cancer." (PMID 29312644, 2017). "We hypothesize that infusion of NK cells expressing high levels of the CXCR2 chemokine receptor will result in increased influx of the transferred NK cells into tumors, and improved clinical outcome in patients with cancer." (PMID 28923105, 2017). "Cancer cells are then attracted to the metastatic site via the CXCL5/CXCR2 axis." (PMID 28186102, 2017). "In addition to IL-8, its receptors CXCR1 and CXCR2 were also reported in human PDAC Capan-1 cells to regulate cancer cell growth, migration, invasion, and its stem cell-like features." (PMID 29379802, 2017). "The expression of CXCL1 in cancer cells was correlated with T invasion (T2–T4), lymph node metastasis, lymphatic invasion, venous invasion, peritoneal cytology, peritoneal metastasis and CXCR2 expression in stromal cells." (PMID 28575019, 2017). "However, up-regulation of CXCR2 has also been correlated with tumorigenesis, cancer tissue angiogenesis, and metastasis of several cancers, including prostate, ovarian, and pancreatic cancers." (PMID 27472713, 2016). "Both IL-8 antibody and CXCR1/CXCR2 antibody combination significantly reduced the sphere number and size of G9a-overexpressing cells indicating that IL-8 is a mediator for G9a to promote cancer stemness via an IL-8/CXCR1/2 signaling axis." (PMID 27531902, 2016). "In addition, CXCR2 is expressed on several carcinomas, and IL-8 signaling promotes proliferation, survival, and invasion of cancer cells as well as angiogenesis within tumors." (PMID 26231560, 2015). "CXCR1 and CXCR2 can mediate migration, invasion, and proliferation individually in cancer cells." (PMID 25852766, 2015). "Both CXCR1 and CXCR2 predominately expressed in cancer tissues." (PMID 26087179, 2015). "CXCR2 predominately expressed in cancer tissue than normal tissue of human lungs." (PMID 26087179, 2015). "CXCR2 has a known role in the recruitment of neutrophils to cancer cells." (PMID 25372289, 2014). "Therefore, based on these functional roles of CXCL1 and CXCR2-mediated signaling in cancer progression, NF-κB potentiation is likely to play a central role in the CXCL1-CXCR2 axis." (PMID 24376747, 2013). "Notably, depleting CXCR2 in MCF-7hPTTG1 cells also strongly activated the phosphorylation of Erk1/2, a signaling protein closely linked to the proliferation status of cancer cells." (PMID 22789011, 2012). "Interestingly, only 40% of the metastatic carcinomas expressed both hPTTG1 and CXCR2 at high levels (2+ and 3+, 20 of 50 in metastatic LNs)." (PMID 22789011, 2012). "Which signalling pathways are activated by CXCL1 through CXCR2 in dendritic cells is yet unknown, however studies in different cell types, such as cancer cells, show that CXCR2 signalling can activate NF-κB, STAT3 and the ERK pathways." (PMID 22125641, 2011). "In addition, skeletal muscle CXCR2 expression is upregulated in a model of cancer cachexia." (PMID 41392310, 2025). "Notably, recent studies have tested the immunotherapeutic potential of anti-CXCR2 blockade using AZD5069 alone or in combination in many human cancers including; head and neck (NCT02499328), pancreatic (NCT02583477), prostate (NCT03177187), liver and herein, the thyroid." (PMID 38900374, 2025). "Cluster 2 contains instead receptor-ligand axes that are more frequently concordantly downregulated in cancer subtypes, although several of these might still be concordantly upregulated in specific subtypes (e.g., CXCR2, EDNRB, FFPR2, or LGR6, GALR2, and UTS2R)." (PMID 38723607, 2024).
cancer (continued). "However, it remains controversial as to whether there is a direct function of either or both CXCR1 and CXCR2 on the growth of the cancer cells, and if so, which of these receptors are involved and what mechanisms are employed." (PMID 37270599, 2023). "Many studies have demonstrated that CXCL5 could promote cancer progression via the receptor CXCR2." (PMID 36151545, 2022). "Also, the increased expression of ligands for CXCR2 in osteocytes under shear stress and PTHrP may support bone metastasis of some cancers, including breast cancer." (PMID 35457023, 2022). "Finally, our results suggest that the use of a CXCR2 inhibitor could correct the effect of JL on cancer-cell dissemination and metastasis." (PMID 32581213, 2020). "However, the biological significance of CXCR2 in cancer cell proliferation remains controversial." (PMID 31788042, 2019). "Therefore, the application of CXCR2-targeted cancer treatment awaits further studies." (PMID 31390756, 2019). "Also, CXCR2 signaling is required for cancer cell proliferation and colonization in bone." (PMID 31562303, 2019). "CXCL5 and its only known functional receptor CXCR2 play a role in promoting angiogenesis, migration, invasion, local recruitment of neutrophils, and poor response to chemotherapies as well as with cancer progression and metastasis in breast, prostate, liver, bladder, and colorectal cancers." (PMID 31562303, 2019). "Likewise, subgroup analyses revealed that CXCR2 was an unfavorable predictor of OS in cancer." (PMID 29599927, 2018). "We demonstrated that CXCR2 might be a prognostic biomarker of some cancers." (PMID 29312644, 2017). "Thus, the inhibition of K327 ubiquitination might emerge as an effective mean to curb exacerbated CXCR2 signaling in several pathological conditions, such as inflammatory diseases and cancer." (PMID 25339290, 2014). "Chemokine CXCL1, also known as Gro-α and MGSA, a ligand of CXCR2, is the best-known CXC chemokine in cancer processes, after CXCL8/IL-8 and CXCL12/SDF-1." (PMID 41898553, 2026). "The recruitment of neutrophils towards transformed or cancer cells depends on interleukin‐8 (IL‐8), which attracts CXCR1/CXCR2‐expressing neutrophils to sites of tissue damage and cancer." (PMID 41503514, 2026). "Aging PSCs exhibit tumor-promoting functions: they promote cancer cell proliferation and migration through the CXCL1/CXCR2 axis." (PMID 40136652, 2025). "Transcriptomic analysis of the microdissected tumors (GSE164665) revealed higher expression of CXCR2, a known receptor for CXCL8, in stromal cells, whereas SLC6A14 was predominantly expressed in cancer cells." (PMID 41444422, 2025). "Interleukin-8 (IL-8), overexpressed in multiple cancer types, recruits neutrophils to the TME through CXCR1 and CXCR2, influencing TAN formation." (PMID 40160822, 2025). "IL-8 attracts immune cells like neutrophils that, instead of fighting the cancer, create an environment through its receptor CXCR1/CXCR2 signaling that helps tumors survive, invade new areas, and avoid immune attack." (PMID 41002568, 2025). "TCGA database indicated that among several ligands, CXCL1, CXCL3, CXCL5, CXCL7 and CXCL8 (ligands for CXCR2) and CCL15 (ligand for CCR1) were particularly upregulated in CRC tissues compared with other cancers." (PMID 38750114, 2024). "Similarly, therapies targeting the CXCR2 signaling pathway, which plays a critical role in the trafficking of neutrophils from the bone marrow into the bloodstream and subsequently into the peripheral tissues, are being actively investigated in various cancers." (PMID 38474175, 2024). "The highest level of CXCL3 was found in PDAC relative to other cancer types, and its receptor CXCR2 (IL8RB, SE = 1.8) was almost exclusively expressed in CAFs." (PMID 38892190, 2024). "Younger patient tumors were only enriched for 3 (5%) of these genes including one cancer testis antigen gene (SSX2) and two genes involved in T-cell recognition and killing of cancer cells (PVR, CXCR2)." (PMID 38975340, 2024).